TXNIP (thioredoxin interacting protein)
Diseases named in the same sentence as TXNIP in open-access papers (continued):
Sharing a sentence is not in itself a finding about the gene and the disease.
Stroke (21 papers, 2016 to 2025). Sudden impairment of blood flow to a part of the brain due to occlusion or rupture of an artery to the brain. "Previously, we and others demonstrated that stroke-induced TXNIP upregulation is associated with increased ischemic injury in normo-glycemic wild-type (WT) mice." (PMID 34681207, 2021). "TXNIP upregulation is associated with blood–brain barrier (BBB) disruption in response to experimental hyperglycemic stroke with an increase of BBB permeability trough the TXNIP / NLRP3 inflammasome axis." (PMID 33567593, 2021). "In the current study, we demonstrated that mice with an endothelial cell selective deletion of TXNIP are more resistant to the neurovascular damage associated with STZ-based HG with tPA-reperfusion in a murine model of embolic stroke." (PMID 34681207, 2021). "Moreover, recent studies have demonstrated that thioredoxin-interactive protein (TXNIP) activation is a key event linked to inflammation; after stroke, it dissociates from the complex and rapidly binds to NLRP3 inflammasome via reactive oxygen species (ROS)." (PMID 27589720, 2016). "By targeting endothelial cells, we aim to determine how TXNIP knockdown promotes neuroprotection, enhances angiogenesis, and reduces inflammation post-stroke." (PMID 39690856, 2025). "The inflammatory responses to brain damage in the etiology of neurodegenerative disease and stroke have been implicated to be mediated by the NLRP3 inflammasome and its activation/related products, TXNIP, ASC specks, caspase- 1, and IL- 1β." (PMID 40272769, 2025). "Earlier studies demonstrated that inhibition of the NLRP3 inflammasome is the primary reason for diminishing TXNIP and stroke-induced injury." (PMID 40272769, 2025). "The Thioredoxin-interacting protein (TXNIP), an inherent regulator of the Thioredoxin (TRX) system, associates with the NLRP3 inflammasome following a stroke, instigating an inflammatory cascade." (PMID 38377025, 2024). "MA at ST36 can improve cognitive dysfunction after stroke by reducing TXNIP related oxidative stress." (PMID 37397457, 2023). "Studies of ours and others have shown thioredoxin-interacting protein (TXNIP) is critically involved in hyperglycemic stroke injury." (PMID 37124219, 2023). "Studies have shown that TXNIP increases in neurodegenerative diseases and cerebrovascular diseases, including Alzheimer's disease (AD), stroke, and subarachnoid hemorrhage (SAH), which induces apoptosis and inflammatory of brain cells." (PMID 35450411, 2022). "TXNIP participates to the progression of several diseases of the central nervous system, such as AD, Parkinson Disease (PD), and stroke." (PMID 34827650, 2021). "Our results support the concept that tPA-reperfusion in HG mice promotes HT and BBB damage after embolic stroke, possibly through TXNIP and upregulating MMP-3/9, and VEGFA expression." (PMID 34681207, 2021). "The mechanism(s) of action by which TXNIP modulates neuronal damage in HG, which is further exacerbated with thrombolytic therapy after embolic stroke are not completely understood." (PMID 34681207, 2021). "Our recent study indicated that genetic or pharmacological ablation of the thioredoxin interacting protein (TXNIP) is associated with suppression of NLRP3 inflammasome and attenuation of stroke outcome." (PMID 29654318, 2018). "Taken together, TXNIP is a central signaling hub that links oxidative/glucose stress and inflammation to cellular injury, making it a “multiple pathways” target and thus a promising new approach for stroke therapy." (PMID 34681207, 2021). "Together, these findings suggest that vascular-TXNIP could be a novel therapeutic target for neurovascular damage after stroke." (PMID 34681207, 2021). "In addition, TXNIP plays a pathological role in several diseases of the central nervous system, such as AD, Parkinson Disease (PD), and stroke." (PMID 34827650, 2021).
Stroke (continued). "Moreover, preclinical studies have shown that TXNIP also increases the expression level of TNF-α in hyperglycemic condition with tPA-reperfusion in stroke." (PMID 34681207, 2021). "Blood TXNIP levels are also found to be higher in stroke patients than in healthy controls." (PMID 33567593, 2021). "Of importance, TXNIP, a redox-regulated protein, can bind to and activate the NLRP3 inflammasome in response to the oxidative stress associated with stroke, and when TXNIP is inhibited, Nrf2 acts as a negative regulator of the NLRP3 inflammasome." (PMID 31998437, 2020). "Consistent with earlier report demonstrating reduced NLRP3 inflammasome activation coincident with neuroprotective modulations, these findings support our presumption that inhibition of NLRP3 inflammasome is the key effector of TXNIP ablation as well as stroke induced injury." (PMID 29654318, 2018). "Moreover, previous reports have demonstrated that TXNIP expression is upregulated in brain tissue after stroke in animals, and ROS induces the dissociation of TXNIP and actives NLRP3." (PMID 27589720, 2016). "The current study found that pre-treatment with the KG diet decreased the production of ROS following stroke and could lower the activation of the TXNIP/NLRP3 inflammasome, suggesting that the KG diet may protect brain damage from ROS-mediated NLRP3 activation." (PMID 40272769, 2025). "TXNIP has been considered an endogenous negative regulator in the TRX system with a pivotal role in central system diseases, such as stroke, subarachnoid hemorrhage, and Alzheimer's disease." (PMID 35571246, 2022). "Activation of TXNIP/NLRP3 inflammasome convert pro-caspase-1 into cleaved-caspase-1 and inhibits the TRX resulting oxidative stress in acute HG suture stroke model." (PMID 34681207, 2021). "TXNIP promotes oxidative stress by inhibiting the thioredoxin (TRX) system, and studies have shown that its expression is upregulated in brain diseases such as stroke." (PMID 36819777, 2023). "For example, increased levels of AMPK following a stroke can inhibit microglial activation and reduce neutrophil infiltration into brain tissue, and AMPK attenuates hippocampal glutamate neurotoxicity by inhibiting ER stress-mediated TXNIP/NLRP3 inflammasomes." (PMID 38069134, 2023). "Further, the KG diet upregulated the HIF-1α and interleukin (IL)-10 expression and inhibited thioredoxin-interacting protein (TXNIP), NOD-like receptor family pyrin domain-containing 3 (NLRP3) inflammasome activation and pro-inflammatory cytokine expression compared to SD-fed mice after stroke." (PMID 40272769, 2025). "Previous research demonstrated that knockout or pharmacological inhibition of TXNIP resulted in restoration of redox balance, inhibition of TXNIP‐NLRP3 pathway, and consequently reduced brain infarction rate and improved neurological scores in embolic stroke model in mice." (PMID 33034416, 2020). "We found that inhibition of TXNIP attenuated HT, BBB dysfunction and brain infarction in hyperglycemic condition with tPA-reperfusion following embolic stroke, indicating that endothelial TXNIP inhibition could be an important target for neurovascular protection in embolic stroke." (PMID 34681207, 2021).
leukemia (20 papers, 2007 to 2025). A malignant (clonal) hematologic disorder, involving hematopoietic stem cells and characterized by the presence of primitive or atypical myeloid or lymphoid cells in the bone marrow and the blood. "In this study, we found TXNIP overexpression causes growth arrest in mixed‐lineage leukemia‐rearranged AML cells." (PMID 32511893, 2020). "MLL‐r leukemia, in which TXNIP expression is most decreased, is caused by translocation of 11q23 with more than 30 different chromosomal sites resulting in MLL fusion genes." (PMID 32511893, 2020). "Previous study has demonstrated its association with the induction of leukemia differentiation, and our own research has previously reported an elevation of TXNIP expression in U937 cells undergoing differentiation in the presence of a pyrimidine synthesis inhibitor." (PMID 37954840, 2023). "TXNIP, a thioredoxin-interacting protein, has been reported to contribute to the growth of leukemia cells." (PMID 40230861, 2025). "The authors showed that ChREBP promotes the differentiation of leukemia-initiating cells (LICs) via the TXNIP/RUNX1 pathways." (PMID 39518998, 2024). "TXNIP-dependent cell differentiation in leukemia and CRC promotes the suppression of leukemogenesis and reduces CRC cell viability." (PMID 37794178, 2023). "Thioredoxin-interacting protein (TXNIP) was first refined from leukemia cells (HL-60) treated with 1,25-dihydroxyvitamin D3 (vitamin D3) and named vitamin D3-upregulated protein-1 (VDUP1)." (PMID 36017183, 2022). "For example, in screening of new disease genes in mouse leukemia caused by a murine leukemia virus (MLV), TXNIP is found to be a common target for MLV integration." (PMID 33194655, 2020). "Thioredoxin interacting protein (TXNIP) was first cloned as an up-regulated gene by 1,25-dihydroxy D3 (Vitamin D3) and named as Vitamin D3 upregulated protein 1 (VDUP1) in the human leukemia cell line (HL-60) derived from a patient with promyelocytic leukemia." (PMID 32824669, 2020). "TXNIP has been shown to be involved in the reactive oxygen-induced stress responses in mouse leukemia." (PMID 33194655, 2020). "We showed that TXNIP overexpression increases sensitivity of leukemia cells to the Bcl‐2 and Bcl‐xL inhibitor, ABT263, by promoting apoptosis induction." (PMID 32511893, 2020). "We have previously reported that mRNA and protein of TXNIP to be lower in either leukemia cell lines or primary bone marrow cells from patients with AML." (PMID 29996811, 2018). "Our study suggests that ChREBP transactivates TXNIP and enhances the production of ROS to promote leukemia differentiation and delay leukemogenesis, although the detailed mechanisms await further investigation." (PMID 27224916, 2016). "ChREBP promoted leukemia cell differentiation through the direct inhibition of RUNX1 or the transactivation of TXNIP to downregulate the RUNX1 level and ROS generation." (PMID 27224916, 2016). "In CML, TXNIP is necessary for the imatinib inhibitory effect on leukemia cell growth." (PMID 39364720, 2025). "Moreover, TXNIP can promote the differentiation of leukemia-initiating cells and CRC cells in glycolysis-independent and glycolysis-dependent manners, respectively." (PMID 37794178, 2023). "Thioredoxin-interacting protein (TXNIP) was discovered as a vitamin D3-stimulated gene in leukemia." (PMID 31208077, 2019). "Because the increased expression of TXNIP may lead to enhanced ROS levels, which is a potent driver of differentiation, we measured the ROS levels in leukemia cells by staining with DCFDA." (PMID 27224916, 2016). "Taken together, all these clues led us to speculate that TXNIP may be a potential target of ChREBP to suppress leukemia development." (PMID 27224916, 2016). "To confirm whether TXNIP is a direct downstream target for ChREBP, we overexpressed TXNIP in ChREBP-null leukemia cells and transplanted them into recipient mice." (PMID 27224916, 2016).
leukemia (continued). "To ask whether TXNIP has a direct impact on the proliferation of leukemia cells, we overexpressed TXNIP in C1498 cells, which is a myeloid leukemia cell line, and demonstrated that the overexpression of TXNIP dramatically inhibited the expansion of C1498 cells in vitro." (PMID 27224916, 2016). "In parallel, TXNIP stabilization upon WWP1 depletion hampers glucose up‐take and glucose metabolism of leukemia cells, with subsequent reduction of ATP production." (PMID 39364720, 2025). "Thioredoxin-interacting protein (TXNIP), which can be induced by high glucose-isomer stimulation, was initially shown to be induced by 1,25-dihydroxyvitamin D3 in the leukemia cell line HL-60." (PMID 38711073, 2024). "High levels of TXNIP also inhibit the proliferation of myeloid progenitor cells, thereby promoting the occurrence and development of AML and MLV-induced mouse leukemia." (PMID 33194655, 2020). "Thioredoxin-interacting protein (TXNIP), initially discovered as a vitamin D3-induced gene in leukemia, was identified as a thioredoxin (TRX)-binding protein by yeast two-hybrid analyses." (PMID 33327533, 2020). "Our results clearly displayed that the mice transplanted with the TXNIP-overexpressing, ChREBP-null AML cells developed leukemia much more slowly than those transplanted with the ChREBP-null control cells, which were comparable to their WT counterparts." (PMID 27224916, 2016). "Thioredoxin interacting protein (TXNIP), also called thioredoxin‐binding protein‐2 or vitamin D3 up‐regulated protein 1, was originally identified as a molecule up‐regulated in HL‐60 leukemia cells by 1,25‐dihydroxyvitamin D3 treatment." (PMID 30410860, 2018). "Noteworthy is that TXNIP was originally identified by Chen and Deluca in 1994 as the vitamin D3-upregulated protein 1 (VDUP1) through screening of regulated cDNAs in response to 1,25(OH)2D3 treatment of HL-60 leukemia cells." (PMID 28124999, 2017). "ChREBP and its downstream molecules, including TXNIP, RUNX1 and GATA2, may be ideal therapeutic targets for certain types of leukemia." (PMID 27224916, 2016). "Consistently, RUNX1, but not GATA2, was remarkably upregulated in ChREBP-null leukemia cells, which could be partially suppressed by the ectopic expression of TXNIP." (PMID 27224916, 2016).
Sepsis (19 papers, 2013 to 2025). Sepsis is defined as life-threatening organ dysfunction caused by a dysregulated host response to infection. "Moreover, high levels of inflammasome activation markers were associated with sepsis-induced myocardial injury, along with increased levels of TXNIP." (PMID 32751530, 2020). "However, whether the TXNIP is involved in the sepsis-induced brain injury and the underlying mechanism is yet to be elucidated." (PMID 35571246, 2022). "Previously noted, TXNIP exhibit a protective negative regulatory role on NO production, induction of iNOS expression as well as on NF-κB activation, while in TXNIP-deficient mice, increased sepsis susceptibility proceed despite reduced IL-1β processing by S-nitrosylation of NLRP3." (PMID 34824200, 2021). "Thus, we believe there is cross-talk between the TXNIP and the NF-κB/iNOS pathways and that this interaction may regulate disease states associated with sepsis." (PMID 24098117, 2013). "In Astrocyte 1, inflammation-associated genes (GFAP, FOS, C3, CD74) were significantly upregulated, while BBB-related genes (GRIA2, NRGN, TXNIP) were downregulated in sepsis." (PMID 41030458, 2025). "The interaction between thioredoxin‐interacting protein (TXNIP) and NLRP3 is crucial for inflammasome activation and participates in inflammatory responses associated with sepsis." (PMID 40264381, 2025). "Research has found that PPARG can reduce pyroptosis and liver damage during sepsis by inhibiting ROS levels and suppressing the TXNIP/NLRP3 signaling pathway." (PMID 40070882, 2025). "Quercetin has been shown to diminish levels of NOX2/ROS-mediated NF-kB/thioredoxin-interacting protein (TXNIP) pathway, thus preventing mitochondrial damage to cardiomyocytes experiencing sepsis-induced pyroptosis in CLP rat models." (PMID 39126050, 2024). "Based on the previous description, LPs-induced Huh7 and HepG2 cells were used to establish cell models of septic liver injury to analyze the role of TXNIP-stabilizing USPs in the progression of sepsis-induced liver injury and in the NLRP3 inflammatory pathway." (PMID 37534934, 2023). "We also observed that TXNIP knockdown upregulated the level of Bcl-2 and downregulated the cleaved caspase-3 and Bax levels in the hippocampus of sepsis mice, thereby inhibiting neuronal apoptosis." (PMID 35571246, 2022). "Secondly, this study only explored the related mechanisms of the neuroprotective effect of TXNIP on sepsis mice with respect to oxidative stress and inflammatory response, while efficiency and other mechanisms need further study." (PMID 35571246, 2022). "In conclusion, the present study demonstrated that the TXNIP knockdown ameliorated sepsis-induced brain injury and cognitive decline by preventing oxidative stress and neuroinflammation in mice." (PMID 35571246, 2022). "Subsequently, TXNIP knockdown significantly improved the 7-day survival rate in sepsis mice, reduced brain edema and hippocampal pathological damage, and improved cognitive dysfunction." (PMID 35571246, 2022). "Herein, we proposed that TXNIP knockdown ameliorates brain injury and cognitive decline after sepsis by regulating oxidative stress and neuroinflammation." (PMID 35571246, 2022). "Firstly, this study only evaluated the effect of TXNIP knockdown on brain damage, and hence, it is necessary to further evaluate the effect of TXNIP overexpression on brain damage in sepsis mice." (PMID 35571246, 2022). "In summary, the present study demonstrated that different phenotypes of macrophages affected the pyroptosis of sepsis‐induced AKI by regulating miR‐93/TXNIP signalling via exosomes delivery." (PMID 33745232, 2021). "This study suggests that TXNIP/NLRP3 signaling is critical for the pathogenesis of sepsis-induced myocardial damage." (PMID 32751530, 2020).